EGFR (epidermal growth factor receptor)
Diseases named in the same sentence as EGFR in open-access papers (continued):
Sharing a sentence is not in itself a finding about the gene and the disease.
ovarian carcinoma (continued). "Although EGFR signaling pathways in ovarian epithelial cancer cells have been described, very little has been shown regarding the signaling pathways activated by TGFα and EGF in GCTs." (PMID 23155381, 2012). "We focussed on NK cell activation as well as natural and antibody-dependent cellular cytotoxicity directed against epidermal-growth-factor-receptor (EGFR)-positive ovarian cancer cell lines." (PMID 23036052, 2012). "In conclusion, our results established that PEITC suppresses the growth of ovarian cancer in vitro and in vivo by inhibiting EGFR signaling." (PMID 22952709, 2012). "Established ovarian cancer cell lines with different EGFR-expression and the chimeric anti-EGFR-antibody cetuximab were used as model for ADCC-based immunotherapy." (PMID 23036052, 2012). "Although little is known about the mechanisms that contribute to ovarian cancer progression, epidermal growth factor receptor (EGFR or ErbB1) is overexpressed in up to 70% of ovarian cancer." (PMID 22860069, 2012). "Our results indicate that PEITC suppress the growth of ovarian cancer cells by disrupting the phosphorylation of EGFR." (PMID 22952709, 2012). "Previously we demonstrated that the ETS family transcription factor PEA3 is regulated by EGFR in ovarian cancer cells and critical to EGFR induced invasion." (PMID 22860069, 2012). "To study the functional effect of MT19c on EGF receptor expression in ovarian cancer cells we examined EGFR localization in SKOV-3 cells in vitro upon treatment with MT19c." (PMID 22509304, 2012). "Membranous EGFR was an independent prognostic factor for poor overall survival in ovarian cancer patients (HR 2.7, CI 1.1-6.4, p = 0.02) which was also found in the serous subtype (HR 4.6, CI 1.6-13.4, p = 0.004)." (PMID 21756326, 2011). "Immunoblotting evaluations of ovarian cancer total cell lysates also demonstrated inactivation of EGFR, ERBB2, and MET after 17-AAG treatment." (PMID 21962244, 2011). "In this study, we demonstrate for the first time an association between EGFR and the nuclear export protein CRM1 in ovarian cancer tissue." (PMID 21756326, 2011). "Three separate experiments were performed to evaluate the reproducibility of detecting the six spiked analytes, in addition to three putative ovarian cancer biomarkers, IL-8, EGFR, and osteopontin, alongside the FDA-approved marker CA-125." (PMID 21834984, 2011). "In ovarian cancer, the reported rate of EGFR expression varies between 4-70% depending on assessment method and data on patient outcome are conflicting." (PMID 21756326, 2011). "A phase I trial combining carboplatin and lapatinib (Tykerb, Tyverb, Glaxo SmithKline, plc, London, UK), an EGFR-Her2 dual inhibitor, was performed in unscreened patients with platinum-sensitive recurrent ovarian cancer." (PMID 21364581, 2011). "We observed a membranous EGFR expression in 36.4% which was an independent predictor of factor for poor overall survival in ovarian cancer patients." (PMID 21756326, 2011). "Amplifications and overexpression of various EGFR family members, including EGFR, Her2, and ErbB3, have been reported in epithelial ovarian cancer." (PMID 21364581, 2011). "We observed a membranous and cytoplasmic EGFR expression in 36.4% and 64% of ovarian carcinomas, respectively." (PMID 21756326, 2011). "We investigated the EGFR protein expression in ten ovarian cancer cell lines as well as in immortalized human ovarian surface epithelium cells (HOSE) by Western Blot." (PMID 21756326, 2011). "We observed high EGFR levels in several ovarian cancer cells in particular in OVCAR-3, SKOV-3, ES-2, OAW-42, CaOV-3, and EFO-27 cells." (PMID 21756326, 2011). "The reduced EGFR protein expression levels after exposure with Leptomycin B in ovarian cancer cells suggest a role of CRM1 in the intracellular transactivation of EGFR." (PMID 21756326, 2011).
ovarian carcinoma (continued). "In this study, we show that membranous EGFR expression is an independent prognostic factor for poor overall survival in ovarian cancer patients." (PMID 21756326, 2011). "In a multivariate Cox regression analysis adjusted for other prognostic factors, membranous EGFR expression was confirmed as an independent prognostic factor for overall survival in ovarian cancer patients." (PMID 21756326, 2011). "EGFR is a tyrosine kinase, which is highly expressed in ovarian cancers, and activates the PI3K-MAPK pathway leading to protein kinase-B (PKB) and Bcl-2-phosphorylation." (PMID 22174601, 2011). "Mutations, amplification, and overexpression of well-known oncogenes, such as PI3K subunit-α, FGF1, MYC, EGFR, KRAS, HER2, and AKT2, have been also associated with ovarian cancer." (PMID 20049170, 2010). "The overexpression of EGFR results in an increased proliferation of solid tumors, including ovarian cancer." (PMID 20509930, 2010). "Since determination of which molecules are key to EGFR signaling in ovarian cancers is not completely understood, the focus will be on inhibition of EGFR and its family members." (PMID 20037743, 2010). "Recent studies have shown that sensitivity of ovarian cancer cells to the taxane, paclitaxel, is enhanced when the drug is administered in combination with an inhibitor of EGFR." (PMID 20064265, 2010). "Among other anti-EGFR antibodies, a single multi-institution open-label phase II trial was reported in patients with ovarian cancer using matuzumab (EMD 72000)." (PMID 20037743, 2010). "Further elucidation of the effects of EGFR signaling in ovarian cancer comes from inhibition of EGFR in cultured human ovarian cancer cells." (PMID 20037743, 2010). "Aberrant epidermal growth factor receptor (EGFR) expression is detected in up to 60% of ovarian cancers and occurs in all histologic subtypes." (PMID 20037743, 2010). "One of the first studies implicating the EGFR pathway in ovarian cancer was the detection of TGF-α in human ovarian cancer effusions as determined by radioimmunoassay." (PMID 20037743, 2010). "Anti-EGFR Monoclonal Antibodies and low-molecular weight Tyrosine Kinase Inhibitors (TKIs) in patients with ovarian cancer." (PMID 24281034, 2010). "The EGFR gene, located on chromosome 7p12, is amplified in ovarian cancer in approximately 4%–22% of cases, including about 13% in epithelial ovarian cancers." (PMID 20037743, 2010). "As EGFR is an extracellular signaling protein, the assays most commonly used in examining EGFR in human ovarian cancer cell lines or tissues involve methods that directly or indirectly measure EGFR activity." (PMID 20037743, 2010). "Studies using a tyrosine kinase inhibitor against EGFR showed an increased sensitivity of ovarian cancer cell lines to paclitaxel after preincubation with the inhibitor." (PMID 20064265, 2010). "Overexpression of the EGFR protein has been detected in 9%–62% of human ovarian cancers; the differences in frequencies from these studies likely reflect utilization of different antibodies and cutoffs for overexpression." (PMID 20037743, 2010). "The present study demonstrates that the inhibitory effect of the GHRH antagonist JMR-132 on proliferation is due, in part, to an interference with the EGFR-Akt pathway in ovarian cancer cells." (PMID 20509930, 2010). "Expression of EGFR was determined by immunoblotting, and the effect of decreased EGFR expression on chemosensitization of ovarian cancer cells after siRNA delivery was investigated." (PMID 20064265, 2010). "It has been also proposed that EGFR plays an important role in ovarian cancer, since this receptor is overexpressed in nearly 75% of primary ovarian cancers." (PMID 20509930, 2010). "The effects observed upon EGFR inhibition were enhanced upon combined treatment of human ovarian cancer cells with the anti-HER2 murine mAb 4D5." (PMID 20037743, 2010).
ovarian carcinoma (continued). "We have previously showed that Lewis(y) antigen stimulates the growth of ovarian cancer cells via regulation of the epidermal growth factor receptor pathway and the PI3K/Akt signaling pathway." (PMID 21151448, 2010). "As detailed by the list of clinical trials, the use of EGFR inhibitors as single agents or in early combination studies in ovarian cancer has met with limited success." (PMID 20037743, 2010). "In the ovarian cancer cell line SKOV-3, CXCL8/IL-8 was shown to induce transient phosphorylation of EGFR and its association with the adaptor molecules Shc and Grb2, suggests an important cross-talk between chemokine and growth factor pathways." (PMID 20049170, 2010). "We report here application of a novel and highly efficient method for the targeted delivery of EGFR siRNA to ovarian cancer cells." (PMID 20064265, 2010). "EGFR-DN was introduced into Caov-3 cells using adenovirus expressing EGFR-DN or by transient transfection of pcDNA3-EGFR-DN with Amaxa nuocleofector Kit T that yield high transfection efficiency in ovarian cancer cell lines." (PMID 20074357, 2010). "We also summarize the results of anti-EGFR therapies in ovarian cancer clinical trials and discuss challenges and future work in effective treatments utilizing anti-EGFR therapies in ovarian cancer, focusing on epithelial ovarian cancer whenever possible." (PMID 20037743, 2010). "EGFR gene amplification or protein overexpression occurs across all epithelial ovarian cancer histotypes." (PMID 20037743, 2010). "EGFR is overexpressed or dysregulated in many solid tumors, and high levels are expressed in 33-98% of all epithelial ovarian cancers." (PMID 20064265, 2010). "While IP tumor implantation offers a model potentially more reflective of advanced ovarian cancer in the patient than subcutaneous injection, the difficulty in measuring tumor volume in intact mice has precluded its widespread use in anti-EGFR drug studies." (PMID 20037743, 2010). "Epidermal growth factor receptor (EGFR) is overexpressed in ovarian carcinomas, with direct or indirect activation of EGFR able to trigger tumour growth." (PMID 19088723, 2009). "As KRAS mutations are associated with poor response and resistance to EGFR-targeting drugs, this study was conducted to obtain more information on the spectrum of KRAS mutations in ovarian carcinoma." (PMID 19358724, 2009). "A significant overall correlation between high levels of P-STAT3, EGFR and IL-6 expression has been reported in ovarian cancer specimens." (PMID 19088723, 2009). "The epidermal growth factor receptor (EGFR) is overexpressed in ovarian carcinoma, and EGFR signalling has been shown to upregulate VEGF expression." (PMID 19002176, 2009). "Two recent reports in ovarian cancer also suggest that increased gene copy number of EGFR is more strongly related to survival than protein expression." (PMID 19513073, 2009). "This warrants exploration into the significance of EGFR-mediated STAT3 activation in the dissemination of ovarian carcinoma." (PMID 19088723, 2009). "Elevated expression of epidermal growth factor receptor (EGFR) and its ligand are common in many epithelial cancers including ovarian cancer." (PMID 19088723, 2009). "Such activation of STAT3 suggests a rationale for a combination of anti-STAT3 and EGFR/IL-6R therapy to suppress the peritoneal spread of ovarian cancer." (PMID 19088723, 2009). "To investigate that, we analysed the activation status of JAK2/STAT3 in ovarian carcinoma specimens and correlated that to STAT3 activation in two ovarian cancer cell lines directly by EGFR or indirectly through IL-6R activation." (PMID 19088723, 2009).
ovarian carcinoma (continued). "The cumulative data in 98 patients thus indicate a 13% rate of high polysomy of the EGFR gene in invasive epithelial ovarian cancer." (PMID 18182111, 2008). "This phenomenon, in a similar manner to that seen in NSCLC, has been observed in a blinded molecular analysis of a Gynecologic Oncology Group (GOG) phase II trial in ovarian cancer with another EGFR inhibitor, gefitinib." (PMID 18506181, 2008). "The absence of these mutations in all but a very rare case of ovarian cancer probably will preclude such dramatic responses upon treatment of ovarian cancer with EGFR tyrosine kinase inhibitors." (PMID 18182111, 2008). "In this study, we investigated the expression and prognostic value of EGFR, EGFR variant III (EGFRvIII), HER-2/neu and important downstream signalling components in a large series of epithelial ovarian cancer patients." (PMID 18628764, 2008). "Despite the well established significance of EGFR in the progression of ovarian cancer, the role of EGF ligands in ovarian cancer is still poorly understood." (PMID 18211683, 2008). "Another report indicated that EGFR downregulation resulted in decreasing E-cadherin and catenins in ovarian carcinoma cells." (PMID 15655536, 2005). "Germline tumour cells harbouring pEGFR-GFP plasmid showed a high level of EGFR expression, which was comparable to that in drug-resistant ovarian cancer (Hey) cells." (PMID 15655552, 2005). "Epidermal growth factor receptor (EGFR) has been implicated in tumour growth and extension of ovarian cancer." (PMID 15827558, 2005). "In contrast, germline tumours expressed very low level of epidermal growth factor receptor (EGFR) compared to drug-resistant ovarian cancer cells." (PMID 15655552, 2005). "In conclusion, these data indicate that the EGFR-targeted tyrosine kinase inhibitor ZD 1839 can inhibit growth of ovarian cancer cells in vitro and in vivo, consistent with inhibition of tyrosine phosphorylation at the EGFR." (PMID 11875715, 2002). "In the present study we have tested its activity against five ovarian cancer cell lines in vitro to assess its growth inhibitory activity and its ability to inhibit TGFα activated EGFR phosphorylation in this disease." (PMID 11875715, 2002). "We have previously demonstrated that one of these inhibitors, ZM 252868 (PD 153035, 4(3-bromoanilino)-6,7-dimethoxyquinazoline) inhibited ovarian cancer cell growth and tyrosine phosphorylation on the EGFR, however this compound was ineffective in vivo." (PMID 11875715, 2002). "In the present study we have explored the potential of a new EGFR targeted tyrosine kinase inhibitor (ZD 1839, ‘Iressa’) to inhibit growth of ovarian cancer." (PMID 11875715, 2002). "The EGFR is reported to be present in between 33 and 75% of ovarian cancers and has been implicated in both the growth and progression of this disease." (PMID 11875715, 2002). "We observed good reversal of EGFR tyrosine phosphorylation produced by TGFα activation in ovarian cancer cell lines and this was consistent with growth inhibition at these concentrations." (PMID 11875715, 2002). "The expression of epidermal growth factor receptor (EGFR), oestrogen receptor (ER) and progesterone receptor (PR) was assayed by a radioreceptor method in 117 primary ovarian cancers." (PMID 7640219, 1995). "Therefore, new approaches to stratify patients and a better understanding of the dysregulated EGFR pathway in ovarian cancer will be critical for improving the efficacy of EGFR-targeted therapy." (PMID 39858026, 2025). "Therefore, new approaches to stratify patients and a better understanding of the dysregulation in the EGFR pathway will be critical for improving the efficacy of EGFR-targeted therapy in ovarian cancer." (PMID 39858026, 2025). "Notably, previous studies have shown that CXCL1 promotes the proliferation of ovarian cancer cells via EGFR activation and mediates adiponectin-induced angiogenesis." (PMID 41360767, 2025).
ovarian carcinoma (continued). "In addition, MEG3 affected the epithelial-mesenchymal transition of ovarian cancer cells by sponging miR-219a-5p and regulating EGFR; low levels of MEG3 and miR-219a-5p were associated with a poor prognosis in patients with ovarian cancer." (PMID 40242248, 2025). "Drug resistance in this tumor model may be explained by overexpression of EGFR, which has been shown to mediate platinum resistance in ovarian cancer cells." (PMID 39639170, 2025). "Moreover, the study conducts a thorough examination of the interactions between the ligand Axitinib alone or after coating with PEG and a diverse array of protein types in breast (Dopamine, VEGFR) and ovarian cancer (EGFR, BCL-xL)." (PMID 40591624, 2025). "The synergistic oncogenic network formed by ZKSCAN3 with EGFR in ovarian cancer reveals a unique mechanism for remodeling the microenvironment through receptor tyrosine kinase signaling in solid tumors, and its functional studies in multiple myeloma further broaden its scope of action." (PMID 40723888, 2025). "We describe here for the first time tumor xenografts in NOD-SCID mice with predefined receptor heterogeneity formed by the s.c. inoculation of mixtures of HER2-positive/EGFR-negative SK-OV-3 human ovarian cancer cells and EGFR-positive/HER2-negative MDA-MB-468 human BC cells." (PMID 38711454, 2024). "Interestingly, SNHG25, known for promoting ovarian cancer progression, and TMEM52B, associated with EGFR and E-cadherin modulation and tumor/metastasis suppression, significantly decreased with KPT-9274 treatment." (PMID 38424218, 2024). "Interestingly, the suppression of EGFR signaling pathway in the dual dose group (RA + DOX) revealed a curious effect of RA in ovarian cancer in the literature." (PMID 38324801, 2024). "Finally, LPA can promote ovarian cancer cell migration by activating an epidermal growth factor receptor (EGFR)‐dependent pathway." (PMID 38480668, 2024). "In another study, OVPDOs were used to identify miRNA interactions with ovarian cancer cells; wide-ranging tumor suppressor effects of specific miRNA were found, and the combination of epidermal growth factor receptor (EGFR) inhibitor had cytotoxic effects on OV-PDOs." (PMID 39358778, 2024). "RA also downregulates the expression level of p-EGFR, EGFR, and Blc-2 in OVCAR3 cells, suggesting that it has anticancer potential for the treatment of ovarian carcinoma, and the underlying mechanism may be related to inhibiting EGFR activation." (PMID 38324801, 2024). "CASC4 may also be a biomarker for predicting response to EGFR inhibitors, which have otherwise seen mixed results as ovarian cancer treatments in clinical trials." (PMID 38030811, 2024). "Moreover, VM specifically targeted tumor sites and expressed MIIP which further reduced the tumor volume of ovarian cancer mice (p < 0.01), via the downregulation of epidermal growth factor receptor (EGFR), Ras, p-MEK, and p-ERK." (PMID 38372808, 2024). "Triple-negative breast cancer (TNBC), endometrial cancer (EC), and epithelial ovarian cancer changes in the epidermal growth factor receptor (EGFR) have been linked to several malignancies." (PMID 39456611, 2024). "Based on our previous work in ovarian cancer we suspected EGFR signaling may differ in Gal3-KO cells compared to their controls." (PMID 38438589, 2024). "Experiments with the EGFR inhibitor AG1478 showed that EGF might promote the progression of ovarian cancer by activating the EGFR-ERK signaling pathway." (PMID 37420173, 2023). "Nevertheless, targeting EGFR has been useful in the treatment of ovarian cancer." (PMID 38203692, 2023). "Further investigations on the mode of action of PEITC revealed that PEITC targets the key signaling pathways of ovarian cancer because PEITC inhibited TGF-dependent activation of EGFR-Akt, and there was significant inhibition of Rictor, Raptor, mTORC1, and mTORC2 thereof." (PMID 37190316, 2023).